HIF1A (hypoxia inducible factor 1 subunit alpha)
Diseases named in the same sentence as HIF1A in open-access papers (continued):
Sharing a sentence is not in itself a finding about the gene and the disease.
colorectal cancer (continued). "Meanwhile, overexpression of RPS7 in colorectal cancer tissues predicts good overall survival and progression-free survival, but high expression level of HIF-1α indicates poor overall survival and progression-free survival." (PMID 26735579, 2016). "Consistently, high-level expression of NQO1 correlates with an increased expression of HIF-1α and poor survival in colorectal cancer patients." (PMID 27966538, 2016). "Consistent with this pro-tumorigenic function for NQO1, high NQO1 expression levels correlate with increased HIF-1α expression and poor colorectal cancer patient survival." (PMID 27966538, 2016). "Investigation of HIF1α in human colorectal cancers of the patient cohort showed an increased expression in all tumor stages (UICC I-IV)." (PMID 27626684, 2016). "Conversely, RKO colorectal cancer cells with suppressed NQO1 expression showed markedly accelerated degradation of HIF-1α." (PMID 27966538, 2016). "Our results provided evidence for LRG1 function as a novel inducer of EMT and angiogenesis in colorectal cancer, which was at least partially through promotion of HIF-1α expression." (PMID 26856989, 2016). "Hypoxia-Inducible Factor 1-alpha (HIF-1α) downregulates c-Myc-mediated activation of hTERT promoter activity in colorectal carcinoma cells." (PMID 27548225, 2016). "We therefore used colorectal cancer cells with the HIF1α gene either deleted or HIF1α and/or HIF2α knocked down to evaluate the effect of HIF1α on lipid metabolites." (PMID 25605240, 2015). "Previous reports have shown that murine PHD1, when overexpressed in colorectal cancer cells, can decrease tumor growth through the reduction of HIF-1α and VEGF." (PMID 26290450, 2015). "To study the role of HIF1α in these processes, we used HCT116 colorectal cancer cells expressing endogenous HIF1α and cells in which the hif1α gene was deleted to characterize HIF1α-dependent and independent effects on hypoxia regulated lipid metabolites." (PMID 25605240, 2015). "Hypoxia-inducible factor-1 is particularly relevant to colorectal cancer, with HIF-1α expression being identified as an independent indicator of poor prognosis in a large prospective study of 731 patients." (PMID 24551593, 2014). "Recently, our research group also reported that SMAD4 suppresses the development of malignant phenotypes of human colorectal cancer through interacting with HIF1α to suppress VEGF and MMP expression under hypoxic conditions." (PMID 24625091, 2014). "These genes, including HIF1-α, VEGF receptors Flt1 and KDR, and VEGFC, suggest an association of FJX1 and angiogenic gene expression in human colorectal cancer tumor samples." (PMID 23922772, 2013). "In the present study, 65 and 47% of colorectal cancer specimens were found to show Annexin A3 and HIF-1α immunoreactivity, respectively." (PMID 24260057, 2013). "It has been shown that HIF-1α-inducible lysyl oxidase activates HIF-1α via PI3K/AKT pathway in colorectal cancer." (PMID 23545606, 2013). "The expression of Annexin A3 and HIF-1α in 60 colorectal cancer tissues was assessed by immunohistochemistry to statistically analyze the association between the clinicopathological features and survival of these cases." (PMID 24260057, 2013). "Stratified analysis of pooled hazard ratios for colorectal cancer patients with overexpressed HIF-1α." (PMID 24324596, 2013). "In head & neck and colorectal cancers HIF-1α staining was less intense (weak to moderate intensity) and involved in smaller areas." (PMID 22804960, 2012). "This was contrary to our expectation, since several previous studies had demonstrated that HIF-1α is involved in cell proliferation and/or tumorigenesis in gastric cancer cell lines, colorectal cancer cell lines, endothelial cell lines and chondrocytes." (PMID 23181099, 2012). "Inverse correlation between the expression of caudal type homeobox 2 (CDX2), a homeodomain protein, and HIF-1α is observed in colorectal cancer samples." (PMID 23241400, 2012).
colorectal cancer (continued). "Galectin-1, one of the important lectins contributing to malignant tumor formation, is induced by HIF-1α to mediate migration and invasion of colorectal cancer cells." (PMID 23241400, 2012). "The present study represents a systematic morphological investigation of HIF-1α in colorectal cancer development." (PMID 18983642, 2008). "Since VEGF promotes lymphangiogenesis and angiogenesis in the primary tumor, thereby paving the way for metastasis, these findings suggest that HIF-1α plays a determinative direct role in the processs of colorectal cancer metastasis." (PMID 18983642, 2008). "HIF-1α activation in colorectal cancer specimens was seen in the vicinity of severe inflammation located in the superficial tumor ulceration and along the invasion pathway." (PMID 18983642, 2008). "We report here that LPS stimulation of diverse colorectal carcinoma cell lines induced HIF-1α expression and translocation to the nucleus." (PMID 18983642, 2008). "In additional in vitro studies, treatment of diverse colorectal carcinoma cell lines with the potent pro-inflammatory factor lipopolysaccharide (LPS) led to HIF-1α expression and nuclear translocation." (PMID 18983642, 2008). "The published data so far concerning a correlation between HIF-1α expression and metastatic disease status of colorectal carcinomas are controversial." (PMID 18983642, 2008). "Eight colorectal carcinoma cell lines are tested for their HIF-1α inducibility after lipopolysaccharide (LPS) stimulation using western blot and immunocytochemistry." (PMID 18983642, 2008). "These researchers and others described a strong association between HIF-1α and VEGF expression in colorectal carcinoma specimens." (PMID 18983642, 2008). "LPS-treatment of the colorectal carcinoma cell lines was due to enhanced perinuclear accumulation and nuclear translocation of HIF-1α 4 hours after stimulation." (PMID 18983642, 2008). "Well-differentiated colorectal carcinoma cell lines were hypoxia-resistent, showing unchanged levels of HIF-1α and VEGF in response to reduced oxygen stress conditions." (PMID 18983642, 2008). "On the same note, the synergistic action of concurrent PDT and chemotherapy on colorectal cancer models underscores the importance of tumor volume reduction of more than 70%, owing to the complementary action of ROS and cytostatic on the HIF-1a signaling pathway." (PMID 41471321, 2025). "The overexpression of HIF1A highlights the role of hypoxia adaptation in colorectal cancer." (PMID 41411347, 2025). "One of the specific studies on CRC proposed that the specific regulatory mechanism of metabolism by microbiota may be the inhibition of glucose metabolism in colorectal cancer cells through the GPR109a-AKT or SIRT4/HIF-1α signaling pathways." (PMID 40927725, 2025). "This is notable since HIF1A is known to promote abnormal angiogenesis in colorectal cancer." (PMID 40650042, 2025). "In addition, HIF-1α recruits cyclin-dependent kinase 8 to stimulate RNAPII elongation in colorectal cancer." (PMID 40484376, 2025). "Furthermore, a correlation is shown to exist between the expression levels of HOTAIR and HIF1A in colorectal cancer cells (correlation coefficient 0.904, p ≤ 0.005) but this measurement is not observed in patients." (PMID 40072116, 2025). "Moreover, the HIF-1α/miR-210/VMP1 pathway is implicated in the migration and invasion of CAFs in colorectal cancer, with potential implications for colorectal cancer metastasis." (PMID 38612567, 2024). "Additionally, a proteomics screen identified Smurf2 (SMAD-specific E3 Ub protein ligase 2) as a HIF-1α interactor that can lead to the degradation of HIF-1α in hypoxic colorectal cancer cells." (PMID 37470788, 2024). "In response to miR-93-5p, XIST adjusts the expression of HIF-1A and promotes the EMT process, proliferation and migration and tumorigenesis of colorectal cancer, suggesting that XIST may serve as a diagnostic and therapeutically relevant marker." (PMID 39830506, 2024).
colorectal cancer (continued). "Genetic variants of HIF‐1α were connected with colon or rectal cancer risk, suggesting that genetic polymorphisms in HIF pathway genes may be connected with colorectal cancer." (PMID 37994607, 2024). "Moreover, it has been demonstrated that HO-1 inhibitor Zinc protoporphyrin was able to reduce colorectal cancer cell proliferation and migration by decreasing HIF-1α and VEGF levels." (PMID 38791428, 2024). "In colorectal cancer, circTDRD3 elevates HIF1α expression by sponging miR-1231." (PMID 39550559, 2024). "Specific to colorectal cancer, increased activity of transcription factor hypoxia inducible factor 1α (HIF-1a) reduces the efficacy of 5-Fluorouracil, the backbone of chemotherapy in colorectal cancer and a radiosensitizer in the context of concurrent chemoradiotherapy (CRT)." (PMID 39330748, 2024). "Taken together, these results indicate that CEACAM6 is involved in an acid- or hypoxia-triggered stress response in colorectal cancer cells but is not linked to HIF1α signaling or under control by CDX1/2." (PMID 38502695, 2024). "XIST modulates via the miR 93-5p the HIF1A-Axl axis in colorectal cancer." (PMID 39639337, 2024). "Furthermore, HIF-1α can promote the recruitment of the histone lysine acetylase TIP60 to chromatin, leading to the acetylation of HIF-1α target genes in colorectal cancer." (PMID 36982369, 2023). "Additionally, GLI2 induced chemoresistance in colorectal cancer through HIF-1α and TGF-β2 signaling pathways." (PMID 37280069, 2023). "Additionally, colorectal cancer liver metastasis facilitating by upregulating Glutaminase 1 (GLS1) in a hypoxia-inducible factor 1α (HIF-1α)-dependent manner." (PMID 37689664, 2023). "These examples demonstrate the relevance of HIF-1α in the hallmarks of colorectal cancer." (PMID 35741024, 2022). "HIF-1α promotes JMJD2B oncoprotein transcription in colorectal cancer-derived tumor cells, triggering a significant increase in cell proliferation and invasion through the overexpression of SLC2A1, SLC2A3, ELF3, UCA1, MET, NOV by removing trimethylation of H3K9 on their promoters." (PMID 35741024, 2022). "As expected, the CT-26 spheroids exhibited no sensitivity to AMG510 under normoxia and hypoxia seeing as CT-26 is a KRASG12D mutant cell line, and previous research has indicated that HIF-1α was induced by KRASG12V signaling at the transcription level in colorectal cancer." (PMID 36550998, 2022). "RPS7 may inhibit glycolysis through HIF-1α-related signaling and thus play a protective role in colorectal cancer." (PMID 36518216, 2022). "The dysregulation of serine/glycine metabolism might lead to a lack of amino acids, followed by an elevated level of ROS, resulting in increased HIF-1α in colorectal cancer." (PMID 35411037, 2022). "Therefore, due to the large number of mechanisms involved in cancer establishment regulated by HIF-1α, it is important to describe their relevance in colorectal cancer." (PMID 35741024, 2022). "Furthermore, the miR-103a-3p/YAP axis was found to promote the expression of hypoxia-inducible factor 1 alpha (HIF1A), consequently enhancing glycolysis and angiogenesis in colorectal cancer cells." (PMID 35701841, 2022). "In addition, ESM-1 expression has been reported to be enhanced by HIF-1α in response to hypoxia in human colorectal cancer and to be mediated by NF-κB in IL-1β-induced inflammatory conditions in human chondrocytes." (PMID 36077661, 2022). "In colorectal cancer, vanillic acid also limits HIF-1α expression." (PMID 34575983, 2021). "Besides, an earlier study reported that brusatol treatment diminished the production of mitochondrial ROS, leading to the activation of PHDs and subsequent degradation of HIF-1α in colorectal cancer cells." (PMID 33542787, 2021). "Findings from this study may provide the basis for developing panaxadiol as a HIF-1α/PD-L1 inhibitor to treat colorectal cancer." (PMID 34575983, 2021).
colorectal cancer (continued). "LncRNA-p21 is a hypoxia-responsive lncRNA that induces HIF-1α accumulation by integrating HIF-1α and Von Hippel–Lindau tumor suppressor (VHL), thus interrupting the VHL–HIF-1α interaction, which promotes glycolysis under hypoxic conditions in colorectal cancer cells." (PMID 33664256, 2021). "In colorectal cancer, imperatorin shows a repressive activity on HIF-1α in hypoxic conditions." (PMID 34575983, 2021). "In addition, dictamnine hinders colorectal cancer growth in conjunction with the downregulation of HIF-1α and snail family transcriptional repressor 2 (SNAI2) expression in vivo." (PMID 34575983, 2021). "In addition, YTHDC2 exerts a promoting role in the colorectal cancer metastasis through the hypoxia/HIF-1α/Twist1 signaling pathway." (PMID 34497675, 2021). "LncRNA SNHG11 promotes invasion and metastasis of colorectal cancer cells by regulating HIF-1α." (PMID 34650600, 2021). "Moreover, it was discerned that LINC00511 is transcriptionally activated by HIF-1α, blocks the function of miR-153-5p, and supports cell survival in colorectal cancer." (PMID 34298879, 2021). "Especially in colorectal cancer, studies on hypoxia-related factors HIF-1α are also notable." (PMID 33801741, 2021). "Also, the miR-675-5p, which is embedded in hypoxia-induced long non-coding RNA H19, is required to sustain the activity of HIF-1α at least in Glioblastoma and Colorectal cancer models." (PMID 33673376, 2021). "To further investigate the molecular mechanism of HIF-1α destabilization by CDK1 or CDK4/6 inhibitors, we performed a proteomic screen on immunoprecipitated HIF-1α from hypoxic colorectal cancer cells that were either untreated or treated with CDK1 inhibitor Ro3306 and CDK4/6 inhibitor palbociclib." (PMID 34611473, 2021). "Furthermore, OSBPL3 is generally considered to be an oncogene factor in colorectal cancer progression, acting through upregulation by HIF1A and activation of the RAS signaling pathway." (PMID 34738015, 2021). "In prostate, lung, and colorectal cancers, miR-21 regulates the expression of HIF-1α and VEGF, but this association was not confirmed in human HCC tissue." (PMID 34440094, 2021). "Moreover, the transcription factor Krüppel-like factor 2 overexpression inhibited proliferation and promoted apoptosis by suppressing the expression of Notch-1 via inhibition of HIF-1α in colorectal cancer cells." (PMID 33542787, 2021). "In addition, a recent study found that HIF-1α induces miR-24 expression in colorectal cancer cells under hypoxic stress." (PMID 32973789, 2020). "We first examined the impact of HSC-CM on HIF-1α expression in HCT116 colorectal cancer cells." (PMID 32895059, 2020). "HIF-1α can also inhibit expression of miR-34a as reported in isogenic colorectal cancer cells." (PMID 32841217, 2020). "In colorectal cancer cells prolidase overexpression was correlated with increased levels of nuclear hypoxia inducible factor 1α (HIF-1α) and HIF-1α-dependent gene products like a vascular endothelial growth factor (VEGF) and glucose transporter-1 (Glut-1)—important factors in cancer progression." (PMID 32710395, 2020). "Moreover, GLS1 is induced by hypoxia via HIF1α in colorectal cancer cell lines, and knockdown of GLS1 reduces metastasis in a xenograft mouse model with colorectal cancer cells." (PMID 32596154, 2020). "The role of Tip60 in HIF-1α activation has been implicated in hypoxia based on the expression of HIF-1α-dependent genes in colorectal cancer cells through mechanisms that are independent of HIF-1α stabilization." (PMID 32927797, 2020). "Another study similarly reported that miR-200b directly targets HIF-1α in colorectal cancer cells." (PMID 31061665, 2019).
colorectal cancer (continued). "miR-31 contributes to colorectal cancer development by targeting factor inhibiting HIF-1α." (PMID 30340459, 2018). "Furthermore, DFO has been shown to increase metastasis in colorectal cancer, most likely through its status as a hypoxia mimetic and increased expression of HIF-1α." (PMID 30506101, 2018). "Here we show that in normoxic colorectal cancer cells, E2 can repress HIF1-α and VEGFA expression." (PMID 29137421, 2017). "We further demonstrated that Smad3 was central to the effects of miR-1 in colorectal cancer cells, establishing a previously unappreciated mechanism by which the miR-1/Smad3/HIF-1α axis facilitates the Warburg effect to promote cancer progression in vitro and in vivo." (PMID 28471448, 2017). "For example, HIF1A (16th by MUFFINN yet below 8000th by all three gene-centric methods in BRCA samples) polymorphism contributes to the risk of gastrointestinal cancer and modulates the response to chemotherapy after surgery in patients with colorectal cancer." (PMID 27333808, 2016). "Therefore, HIF-1α is a rational target for the development of new therapeutics for colorectal cancer." (PMID 27144516, 2016). "Thus, we sought to determine if HIF-1α expression correlates with NQO1 levels in human colorectal cancers." (PMID 27966538, 2016). "In addition to promoting EMT in colorectal cancer via activation of HIF-1α by Hsp90, several reports have also demonstrated that Hsp90 promotes α-SMA and p-p38 expression and reduces that of E-cadherin in HCC cells, thereby promoting EMT." (PMID 27248828, 2016). "In this study, we demonstrate that RPS7 inhibits the colorectal cancer (CRC) cell glycolysis by suppressing the expression of hypoxia-inducible transcription factor-1α (HIF-1α) and the metabolic promoting proteins glucose transporter 4 (GLUT4) and lactate dehydrogenase B (LDHB)." (PMID 26735579, 2016). "Moreover, HIF-1α competes with transcription factor 4 (TCF4) for direct binding to β-catenin thereby enhancing EMT in colorectal cancer." (PMID 26057751, 2015). "Mortality of colorectal cancer patients has previously been demonstrated to be associated with high HIF-1α, but not HIF-2α, mRNA and protein levels." (PMID 25978030, 2015). "The mouse model of colorectal cancer used in this study shows similar features: HIF-2α mRNA levels in MC-38 colon adenocarcinoma cells were at least two orders of magnitude lower than the HIF-1α mRNA levels." (PMID 25978030, 2015). "In this study, we undertook a retrospective observational analysis of tissue-banked tumor and paired normal tissue from 49 colorectal cancer patients, measuring ascorbate levels, HIF-1α and its downstream gene products BNIP3, and vascular endothelial cell growth factor (VEGF)." (PMID 24551593, 2014). "In this study, the expression of Annexin A3 and HIF-1α was detected in colorectal cancer." (PMID 24260057, 2013). "The objective was to ascertain whether Annexin A3 is involved in the progression of colorectal cancer, and to investigate its correlation with HIF-1α." (PMID 24260057, 2013). "Furthermore, Annexin A3 and HIF-1α protein expression exhibited a similar pattern in these samples, and their expression was found to correlate with poor survival in colorectal cancer patients." (PMID 24260057, 2013). "In total, 60 colorectal cancer samples were detected for Annexin A3 and HIF-1α staining." (PMID 24260057, 2013). "In addition, Annexin A3 and HIF-1α proteins appear to be important in the advancement of colorectal cancer." (PMID 24260057, 2013).